CD4 (CD4 molecule)
Diseases named in the same sentence as CD4 in open-access papers (continued):
Sharing a sentence is not in itself a finding about the gene and the disease.
anemia (continued). "Another clinical reason could be that CD4 cell count is significantly associated with the likelihood of anemia; this is explained by an increased viral burden, which may cause anemia through increased cytokine-mediated myelosuppression and a higher burden of OIs." (PMID 37205221, 2023). "Collectively, these data indicate that anemia during experimental murine visceral leishmaniasis can be driven by defects associated with the bone marrow erythropoietic niche, and that this represents a further example of CD4+ T cell-mediated immunopathology affecting hematopoietic competence." (PMID 30619317, 2018). "There may be important biological implications to our finding that the mean hemoglobin level increased with increasing CD4 count, and that lower CD4 count was associated with an increased risk of anemia, in other words that the prevalence and severity of anemia increased with decreasing CD4 count." (PMID 24058490, 2013). "The majority (79.39%) of children had CD4 cell count above the threshold, and about 16.05% had anemia; 30.8% and 48.9% nutritional statuses were wasted and stunted, respectively." (PMID 40055762, 2025). "A previous study identified advanced age, low CD4+ counts, underweight, low CSF pressure, and anemia as predictors of mortality in HCM patients." (PMID 41425969, 2025). "WHO clinical stages, Anemia, CD4 cell counts, and developmental milestones were significant predictors of mortality." (PMID 39854472, 2025). "In the bivariate analysis, age of child, relationship of children with caretakers, parental status, ART experience, CD4 count, history of OIs, poor adherence, ADR, and anemia were moderately associated with virologic failure." (PMID 41332892, 2025). "These variables were ART drug adherence, delayed developmental milestone, WHO Clinical stages, presence of Anemia, CD4 Cell Count, and under nutrition." (PMID 39854472, 2025). "Our findings highlight the critical role of CD4 count, serum iron, and ferritinemia in the development of anemia." (PMID 40809818, 2025). "In the present study, inverse significant correlations are noticed between CD4 with MDA, TNF- α and sTfR/log ferritin denoting that oxidative stress, inflammation and anemia in PD are associated with reduced CD4." (PMID 40615531, 2025). "Anemia is the earliest and most common hematologic abnormality; affecting 60–90% of patients in the late-stage disease with lower CD4 count." (PMID 39480901, 2024). "African American ethnicity, age, overweight, history of pneumonia, oral candidiasis, history of fever, ZDV usage, low CD4+ cell counts (200 cells/mL), and greater HIV-1 RNA levels in plasma all enhance the risk of anemia." (PMID 38903363, 2024). "We found that the risk factors for discontinuing TDF were older age, presence and severity of anemia, low baseline eCrCl, and CD4 cell count <200 cells/μl." (PMID 38175824, 2024). "All six patients were anaemic compared to a 76% prevalence of anaemia in the remainder of the cohort, and these patients had lower median CD4 counts compared to the remainder of the cohort." (PMID 38399965, 2024). "While hospitalized, he developed anemia and severe thrombocytopenia, with a CD4 count of 1 cell/mm3, requiring hemotransfusion and vasoactive drug therapy." (PMID 39186781, 2024). "After 2.5 months of ART and one month of specific treatment for the lymphadenitis, he had marked mass reduction, improved adenopathy, increased CD4 count, correction of anemia, and resolution of his acute malnutrition." (PMID 38678293, 2024). "Chinese HIV patients, especially those with TB, TM infection, and low CD4 levels, should be routinely detected for anaemia to improve therapy." (PMID 36413338, 2023). "Other factors including older age, female, acquired HIV through heterosexual contact or injecting drug use, low BMI, low eGFR, low CD4+ T cell count and high viral load were independent predictors of anemia." (PMID 37858044, 2023).
anemia (continued). "We report a 6-year-old patient with a recurrent respiratory infection, cryptosporidium enteritis, lymphoproliferation, high serum immunoglobulin-M level, anemia, and inverted CD4+/CD8+ ratio." (PMID 36749229, 2023). "The majority had low mean CD4 counts, unsuppressed VLs, and CDC Stage 3, which are indicative of advanced HIV disease and a high risk of anaemia." (PMID 36834279, 2023). "The underlying diseases and risk factors for emergomycosis in the HIV-infected patients were CD4+ T-cell counts (<100 cells/mm3), anaemia, and thrombocytopenia." (PMID 37888295, 2023). "Data on demographic characteristics, related factors of anemia, latest hemoglobin, CD4, and ART regimens were collected using a structured data abstraction format." (PMID 37868338, 2023). "Corroborating with this idea, a retrospective cohort study of persons with advanced HIV (CD4 <100 cells/μL) reported that those with TB diagnosis more frequently had anemia and exhibited more pronounced inflammatory profile than those without this comorbidity." (PMID 37143662, 2023). "The risk factors for emergomycosis in HIV-infected patients were CD4+ T-cell counts (<100 cells/mm3), anaemia, and thrombocytopenia." (PMID 37888295, 2023). "In patients with the concurrent OIs, baseline eGFR < 60ml/min/1.73m2, baseline BMI < 18.5 kg/m2, baseline CD4+ T cell count < 200 cells/μL or age ≥ 50 years, the proportion of total anemia was 61.4%, 58.2%, 50.6%, 47.8% and 41.6%, respectively." (PMID 37858044, 2023). "Having HIV infection for at least five years, a CD4 cells count below 200 cells/mm3, being on at least clinical stage III, and having a BMI below 18.5 kg/m2 were found to be associated risk factors of anemia among HIV-infected adults in SGH." (PMID 38085717, 2023). "That is, these parameters showed a tendency to increase (in the case of female frequency, CMV detection, Mtb blood culture and Urine Mtb Xpert positive result) or decrease (CD4 count) as anemia severity worsened." (PMID 37143662, 2023). "The prevalence of laboratory tests were as follows: albumin <35 g/L (55.6%), erythrocyte sedimentation rate >20 mm/h (91.4%), anaemia (59.0%), predominantly mild, CD4+ T cell count ≤50 pieces/μL (70.3%), and CD4+ T cell count 51-200 pieces/μL (22.1%)." (PMID 37651639, 2023). "In the final model of the multivariable logistic regression analysis, CD4 count, WHO clinical stage, cotrimoxazole preventive therapy and MUAC of the child were the significant factors associated with anaemia among seropositive children after starting HAART." (PMID 37706072, 2023). "The present study found that CD4 count, WHO clinical stage, cotrimoxazole prophylaxis therapy and MUAC were significantly associated with anaemia in children on ART." (PMID 37706072, 2023). "The proportion of anemia was higher in concurrent OIs group, the older age group, the lower baseline eGFR, BMI or CD4+ T cell count group." (PMID 37858044, 2023). "Underweight is more common among HIV-positive adults with advanced disease stages, anemia, diarrhea, serum albumin < 3.5mg/dl, CD4 count of less than 200 cells/mm3, eating problems, drug non-adherence, and smokers." (PMID 37733681, 2023). "In the present study, CD4 count, WHO clinical stage, CPT and MUAC were significantly associated with anaemia among HIV-positive children on HAART." (PMID 37706072, 2023). "The causes of anemia in HIV-infected patients are multifactorial, including HIV infection, aging, poor nutritional status, advanced disease, lower CD4+ T cell count as well as antiretroviral drugs." (PMID 37858044, 2023). "The prevalence of anemia in MHC patients was higher in CD4 count of ≤500 cells/μl (59.3%) as compared to those with ≥500 (40.7%)." (PMID 35245289, 2022). "Strong evidence for univariable associations between each of CD4 count, BMI, TB-related symptoms, detectable urine LAM, and anemia was observed." (PMID 35855000, 2022).
anemia (continued). "Accordingly, low blood Hb and anemia were associated with a higher clinical TB score and ESR levels, but with reduced BMI and MUAC, along with low CD4 and CD8 T cell counts and lower IFN-γ levels." (PMID 36014824, 2022). "The relationship between the CD4:CD8 ratio and anaemia has been evaluated mostly in the context of iron deficiency." (PMID 35022106, 2022). "Multivariate logistic regression analysis shows that TDF based ART regimen and advanced disease (low baseline CD4 cell count) were independent predictors of anemia." (PMID 35333889, 2022). "FeLV or FIV infected cats treated with recombinant human interferon-α improved in terms of most of the parameters analyzed (clinical status, anemia, white cell counts and CD4+/CD8+ ratio) in another study, similar to that described previously in FeIFN-ω." (PMID 35158547, 2022). "In patients with CD4 count ≥500 anemia was 44.08% (25.8% in MHC and 18.3% in OH) but anemia was 55.9% in those with CD4 count of ≤500." (PMID 35245289, 2022). "Accordingly, low hemoglobin level is an adverse prognostic marker in HIV patients, and identifying and treating patients with anemia can improve the CD4 cell count, increase immune function, and delay disease progression." (PMID 35846073, 2022). "Generally, anemia in patients with CD4 counts of ≤500 and ≥500 cells/μl was 56% and 44% respectively." (PMID 35245289, 2022). "The current research findings indicated that a lower CD4 count was an independent correlate of anemia in HIV-infected patients." (PMID 36474196, 2022). "The current study found that, HIV-infected individuals had high SHR compared HIV-uninfected individuals especially those with moderate or severe anaemia, low BMI, and low CD4 counts, indicating that HIV-infected patients are at a higher risk of NCDs." (PMID 35061774, 2022). "Anemia in MHC patients was higher in those with CD4 count of ≤500 cells/μl (59.3%) while in OH (Only HIV infected) anemia prevalence was similar in those with CD4 count of ≤500 and ≥500 cells/μl (50%)." (PMID 35245289, 2022). "The main factors correlated to lower physical activity and capacity in HIV-infected were low BMI, anaemia, low CD4 counts as a marker of disease progression, and increased CRP as a marker of inflammation." (PMID 35061774, 2022). "In multivariable analyses, lower CD4 count, lower BMI, presence of TB-related symptoms, detectable LAM, and more severe anemia were strong risk factors for shorter time to hospitalization/death." (PMID 35855000, 2022). "The currently reported associated risk elements for anemia include gender, age, income level, impact of antiretroviral therapy (ART) drugs, CD4 count, HIV viral load, and opportunistic infections (OIs)." (PMID 36474196, 2022). "Study from Cameroon and Ethiopia demonstrated correlation of CD4 count and anemia in HIV infected patients before starting ART." (PMID 35245289, 2022). "The prevalence of anemia was 17.21%, 20.30%, 25.81%, and 33.75% in patients with CD4 counts of > 350, 200–350, 50–199, and < 50 cells/μl, respectively." (PMID 36474196, 2022). "We have recently shown that HIV-negative TB patients with anaemia were more likely to have low CD4 T-lymphocytes at the NTTC." (PMID 35022106, 2022). "Low baseline CD4 cell count and tenofovir based regimen were independent predictors of anemia; while being educated was protective." (PMID 35333889, 2022). "Anemia was associated with a low body mass index (BMI), low mid-upper arm circumference (MUAC), lower peripheral CD4 and CD8 T cells counts and IFN-γ levels, and a higher erythrocyte sedimentation rate (ESR)." (PMID 36014824, 2022). "Anemia in subjects with CD4 of 200–499 was 45.1%, this was higher than 39.3% of similar study of Ethiopia but similar with 44% of anemia in similar CD4 count in Central Tanzania." (PMID 35245289, 2022).
anemia (continued). "Anemia prevalence distribution among sex showed that 61.3% in female sex and anemia prevalence distribution among CD4 group showed 55.9% in patients with CD4 count of ≤500 cells/μl." (PMID 35245289, 2022). "CD4 count <100 cells/μL and presence of anemia appeared to have the greatest population impact on rates of hospitalization/death (PAF 38% and 48%, respectively; 95% CI, 20%–53% and 34%–80%)." (PMID 35855000, 2022). "At a 1:10 of T cells to CECs ratio, similar to that observed in anemia, CECs completely suppressed the proliferation of CD4+ and CD8+ T cells." (PMID 34893694, 2021). "The median survival time free from anemia among children who had a CD4 count below the threshold level was 62 months, but 125 months for those who had a CD4 count above the threshold level." (PMID 33785009, 2021). "The median survival time free from anemia was significantly longer in persons with a CD4 count above the threshold level." (PMID 33785009, 2021). "Using univariate logistic regression: anemia, increases in erythrocyte sedimentation rate (ESR), CD4 cell count, HIV Viral load were associated with positive results of GeneXpert and smear AFB." (PMID 33503051, 2021). "The rest of the variables (age, maternal anemia, gravidity, low birth weight, IPTp treatment, seasonality; and CD4+ T cell counts, ART and viral load for HIV-infected women) did not provide any added value to the multivariable models and were not included." (PMID 33746958, 2021). "The results of the patient's complete blood count revealed anemia and leukopenia and CD4 lymphocytes: 79 cells/μL." (PMID 34007498, 2021). "This study also revealed that undernutrition is more common among HIV-positive adults with advanced disease stage, anemia, diarrhea, CD4 count less than 200 cells/mm3, and living in rural areas." (PMID 32322404, 2020). "Nonetheless, injection substance users with CD4 <350 cells/uL were highly associated with anaemia, a finding in agreement with previous studies which have reported CD4 <350uL as one of the major predictors of anaemia among injection substance users." (PMID 33911826, 2020). "We observed that treatment was well tolerated by the cats (as it did not affect the liver or the kidney functions), and improved most of the parameters analyzed (clinic, anemia, white cell counts, and CD4+/CD8+ ratio) as long as it was administered." (PMID 32825496, 2020). "Being on baseline advanced WHO stages, lower baseline CD4 count, and baseline anemia was found to be the statistically significant independent risk factors of EPTB." (PMID 32374773, 2020). "rHuIFN-α treatment improved the anemic processes observed at M0 (at least in cats with mild or moderate anemia) and leukocyte counts, including a more favorable CD4+/CD8+ ratio." (PMID 32825496, 2020). "Similar to other studies findings, we found that the prevalence of anemia was significantly higher as the CD4 T cell count of the study participants decreased and WHO clinical stage advanced." (PMID 32931523, 2020). "Although HAART has the capability of reducing the incidence of anemia by suppressing viral replication and increases CD4 cell count, anemia remains a common problem even for patients treated with antiretroviral agents." (PMID 32148954, 2020). "Moderate to severe anemia was a stronger predictor than CD4 count and overall was the strongest predictor of early ART mortality in our cohort, similar to other studies in SSA." (PMID 33161899, 2020). "Group 1 (lowest mortality risk, 9.8% [5/51]) were more likely to be ART naive, have better functional status and nutrition (higher MUAC and BMI), less severe anemia, and higher CD4 cell count." (PMID 31781758, 2020). "Anaemia, lower Red blood cells and platelets counts correlated with mortality in the first year of care, independently by body mass index, haemoglobin, CD4+ count and VL." (PMID 33170905, 2020).
anemia (continued). "A study done in Ethiopia reported similar findings that having low CD4+ T cells count level (<200cells/mm3) and being HAART-naïve, were significantly associated with anemia." (PMID 32228523, 2020). "At baseline, our study showed that WHO stage, BMI category, education and CD4 count were significant predictors of anaemia." (PMID 33425126, 2020). "For example, baseline anemia (Hgb < 10 g/dL), low CD4 count, advanced WHO clinical disease staging (III & IV), poor ART drug adherence, and malnutrition were reported as factors significantly increasing risk of mortality in HIV-positive children receiving ART." (PMID 32854692, 2020). "This study also revealed that undernutrition is more commonly prevalent among HIV-positive adults with advanced disease stage, having anemia, having diarrhea, CD4 count less than 200 cells/mm3 and living in rural areas." (PMID 32322404, 2020). "The following characteristics were significantly associated with anaemia at baseline: Body mass index (BMI) category (p=0.01); World Health Organization (WHO) stage (p=0.001) and CD4 count (p=0.001)." (PMID 33425126, 2020). "Other researchers further reported that more severe levels of anemia are found among HIV positive patients presenting with low CD4 count level." (PMID 32228523, 2020). "Second, some baseline characteristics namely; body mass index, CD4 count, anaemia and Hepatitis B and C co-infections were incomplete in at least 80% of the records and were excluded from analysis." (PMID 32934801, 2020). "Anemia, OIs, low CD4 counts or percentages, advanced disease staging (III and IV), severe stunting, and severe wasting were factors found as significantly increasing the risk of mortality among HIV-infected children receiving ART." (PMID 32854692, 2020). "In conclusion, these results indicate that weight loss, severe anemia and microcytic hypochromic anemia are the most common anthropometric and erythrocytic deviations among HIV and TB co-infected ISUs with CD4 T-cells < 350/uL in the Kenyan Coast." (PMID 33911826, 2020). "Anemia was more common among CD4+ T‐cell cases in the outcome cohort (28% cases affected) compared to the concordance cohort (9% cases affected; P = .01), but anemia incidence was not significantly different for other phenotype groups." (PMID 31693230, 2020). "The levels of HB decreased with low CD4+ counts in the HIV-infected individuals and supports previous reports which suggest that anaemia in HIV-infected patients is associated with poor disease outcomes." (PMID 31339937, 2019). "The aim of this study was to determine the prevalence of intestinal parasitic infections in relation to CD4 count and anemia among ART-initiated patients in St." (PMID 31029088, 2019). "Prevalent TB was also more common among patients with pre-ART CD4+ count < 50 cells/mm3 and anemia at baseline." (PMID 31409289, 2019). "Nonetheless, the conclusions when using a binary outcome remain the same (Unadjusted Odds Ratio = 1.11[0.61–2.04], p = 0.73; Odds Ratio adjusted for CD4 counts and anemia = 0.99[0.50–1.95], p = 0.98)." (PMID 30866830, 2019). "Whereas factors associated with anemia after initiation of HAART were being male sex, drug regimen, increased age and CD4 count less than 200cell/ul and 200-350cell/ul." (PMID 31596865, 2019). "In this study, old age (≥ 50 years), stage IV HIV disease and CD4+ T-cell count <200 cells/mm3 were identified as independent predictors of anemia." (PMID 30759131, 2019). "After univariable analysis, female sex, lower peak CD4 counts, lower current CD4 counts, anemia, and shorter time infected with HIV-1 were all significantly associated with higher viral load." (PMID 30866830, 2019). "The levels of HB, MCV and MCH decreased with low CD4+ counts in the HIV-infected individuals and supports previous reports which suggest that anaemia in HIV-infected patients is associated with poor disease outcomes." (PMID 31339937, 2019).